PF4 (platelet factor 4)
Diseases named in the same sentence as PF4 in open-access papers (continued):
Sharing a sentence is not in itself a finding about the gene and the disease.
pancreatic cancer (12 papers, 2011 to 2025). "For example, in patients with pancreatic cancer, elevated levels of platelet factor 4 (PF4) were found, and these elevated levels were associated with an approximately threefold increase in the risk of VTE." (PMID 37513923, 2023). "One study also suggested that high amounts of PF-4 (Platelet Factor-4) were associated with an increased risk of venous thromboembolism (VTE) in pancreatic cancer patients." (PMID 30441823, 2018). "CXCL4/PF4 was identified and confirmed as a new discriminating marker for pancreatic cancer using MALDI-TOF MS." (PMID 25298751, 2014). "Other proteins were also identified as new potential discriminating markers of pancreatic cancer, such as phosphoglycerate kinase (PGK) 1, histone H4 cyclin I, Rab GDP dissociation inhibitor b (GDI2), and serotransferrin platelet factor 4 (PF4)." (PMID 22084685, 2011).
coagulopathy (11 papers, 2017 to 2025). "A vaccine-associated coagulopathy was suspected due to the detection of platelet-factor 4 IgG antibodies and a positive platelet factor 4 enhanced heparin-induced platelet activation (PIPA) test, which occurred after the spontaneous intracranial bleeding." (PMID 36982716, 2023). "Given that PF4 and HMGB1 induce NET formation, PF4+ and HMGB1+ pEVs contribute to NET-associated coagulopathy." (PMID 35874830, 2022). "More work is required in the group with coagulation disorders such as decreased anti-thrombin (heparin resistance), PF4-heparin antibodies and elevated fibrinogen." (PMID 28219324, 2017). "Depending on the cut-off values used, between 30 and 75% of people vaccinated against SARS-CoV-2 develop autoantibodies against PF4 but do not display any coagulopathy symptoms." (PMID 36232795, 2022).
dengue (11 papers, 2014 to 2025). "STXBP5 knockout in mice reduces platelet factor 4 (PF4/CXCL4) secretion, mirroring the observed PF4 reduction, which correlates with dengue severity." (PMID 41583452, 2025). "We then quantified the levels of the chomokines RANTES/CCL5 and PF4/CXCL4 secreted ex vivo by platelets isolated from dengue-infected or HIV plus dengue-coinfected patients." (PMID 31068600, 2019). "In agreement, we also observed exhaustion of the granule-stored chemokine PF4/CXCL4 in platelets from patients with dengue." (PMID 28542641, 2017). "PF4V1/CXCL4L1, a variant of PF4/CXCL4, was found to be down-regulated in platelets from dengue patients compared to control." (PMID 28542641, 2017). "Consistent with this, plasma levels of PF4/CXCL4 were increased in dengue-infected patients compared to healthy volunteers." (PMID 28542641, 2017). "A recent study reported that patients with severe dengue have lower levels of PF4/CXCL4 in plasma when compared to mild dengue patients." (PMID 28542641, 2017). "Platelet exhaustion of PF4/CXCL4 content occurred in parallel with increased PF4/CXCL4 in plasma from dengue patients and PF4/CXCL4 secretion by platelets that were activated by DENV infection in vitro." (PMID 28542641, 2017). "ROC curve analysis was used to determine AUCs and specificity/sensitivity values for OLFM4 and PF4 as prognostic biomarkers of disease severity in Cambodian acute patients with dengue." (PMID 26572220, 2015). "Further prospective studies are warranted to confirm and validate the prognostic value of OLFM4 and PF4 as potential biomarkers of disease severity in larger cohorts of patients from a variety of dengue-endemic areas around the globe." (PMID 26572220, 2015). "Analysis of a selection of the identified proteins using ELISAs identified two host proteins, OLFM4 and PF4, which had significant prognostic value for classifying patients with dengue who were likely to develop SD." (PMID 26572220, 2015). "Median levels of Angptl3, IL-18BP, CXCL10, Platelet Factor 4, sICAM-1, Factor D, sEng and sKDR were higher in dengue fever compared to leptospirosis (p < 0.001 for all)." (PMID 24444080, 2014). "Downregulation of PF4/CXCL4 gene by two folds following the treatment with FCPLJ in dengue infected mice in this study showed that FCPLJ could has suppressed the expression of PF4/CXCL4 gene to increase platelet production during dengue infection." (PMID 30744623, 2019). "Furthermore, it was reported that PF4/CXCL4 was increased in plasma of dengue patients compared to healthy volunteers." (PMID 30744623, 2019). "Likewise, western blot analysis of PF4/CXCL4 revealed lower PF4 quantities in platelets from patients with dengue compared to healthy volunteers." (PMID 28542641, 2017). "Importantly, activated platelets from patients with dengue released higher levels of PF4/CXCL4 ex vivo when compared to control platelets, despite reduced PF4 content." (PMID 28542641, 2017). "This may result from lower platelet counts in patients with severe dengue, or from enhanced platelet exhaustion of PF4/CXCL4 content in severe dengue patients." (PMID 28542641, 2017). "Among 22 host proteins tested, two could differentiate between dengue fever and severe dengue in two independent cohorts (olfactomedin-4: area under the curve (AUC), 0.958; and platelet factor-4: AUC, 0.836)." (PMID 26572220, 2015). "Therefore, a basal level of PF4 expression during the acute phase of DV infection could be an interesting marker of a future severe dengue." (PMID 26572220, 2015). "Of note, the chemokine PF4/CXCL4 is exclusively expressed by platelets and megakaryocytes, and its lower levels in plasma suggests defective platelet responses in HIV plus dengue coinfected patients." (PMID 31068600, 2019).
dengue (continued). "Even though most of the chemokines were present at similar levels in samples from dengue infected and HIV plus dengue coinfected patients, the platelet-derived chemokines PF4/CXCL4 and RANTES/CCL5 were reduced in patients coinfected with HIV when compared to patients infected with DENV only." (PMID 31068600, 2019). "Consistently, dengue plus HIV coinfected patients also presented lower levels of plasma pro-inflammatory cytokines (IFN-γ and IL-1β) and platelet-derived chemokines (RANTES and PF4) when compared to patients infected with DENV only." (PMID 31068600, 2019). "Among stored factors, platelets from dengue-infected patients and platelets infected with DENV in vitro have been shown to secrete higher levels of the co-stimulatory molecule sCD40L and the chemokines PF4 and RANTES35,69." (PMID 31068600, 2019). "Our finding of elevated levels of PF4 in dengue, but not leptospirosis, suggests a role of PF4 as a mediator of innate immunity or pathogenesis in dengue virus infection." (PMID 24444080, 2014). "Nine biomarkers differed significantly between dengue fever and leptospirosis, with higher levels of Angptl3, IL-18BP, IP-10/CXCL10, Platelet Factor 4, sICAM-1, Factor D, sEng and sKDR in dengue and higher levels of sTie-2 in leptospirosis (p < 0.001 for all comparisons)." (PMID 24444080, 2014). "Platelets isolated in the acute phase from dengue-infected patients, but not platelets from HIV plus dengue-coinfected patients, released higher levels of PF4/CXCL4 and RANTES/CCL5 when incubated ex vivo compared to platelets from the same patients collected and examined at the recovery." (PMID 31068600, 2019). "However, when platelets isolated from patients were incubated ex vivo, platelets from coinfected patients secreted lower levels of RANTES/CCL5 and PF4/CXCL4, but not IL-1β, compared to patients with dengue without HIV coinfection." (PMID 31068600, 2019). "Finally, the platelet alpha granule factor PF4 was increased in dengue fever relative to healthy controls, but not in leptospirosis." (PMID 24444080, 2014).
melanoma (11 papers, 2014 to 2025). A malignant, usually aggressive tumor composed of atypical, neoplastic melanocytes. "In contrast, tumorigenesis induced by intradermal injection of B16F10 melanoma cells was associated with blood-filled lymphatics in approximately 33% of Pf4 CLEC-2-deficient mice compared to wildtype mice." (PMID 32129691, 2021). "Stable Pf4 silencing significantly promoted melanoma cell metastasis in NOD/SCID mice shifting from single-organ limited metastasis seen in the control group (OL-NC and POL-Sec23a-NC) to multi-organ extensive metastasis." (PMID 34421345, 2021). "Taken together, these results indicate that secreted PF4 acts downstream Sec23a to mediate its inhibition of melanoma cell migration and invasion in vitro." (PMID 34421345, 2021). "We compared Ppbp and Pf4 mRNA expression between melanoma and melanocyte and between the low-invasive and high-invasive melanoma, respectively using GEO database." (PMID 34421345, 2021). "We conducted experiments and show that MAPK/ERK signaling mediates the inhibitory effect of secreted PF4 on the invasive behavior of melanoma cells." (PMID 34421345, 2021). "Second, MAPK/ERK signaling mediates the inhibitory effect of secreted PF4 on the invasive behavior of melanoma cells." (PMID 34421345, 2021). "In summary, our data show that secretory Pf4 inhibits the metastatic progression of melanoma cells via inactivation of the MAPK signaling pathway." (PMID 34421345, 2021). "In summary, our data collectively demonstrate that Pf4 inhibits metastatic capability of melanoma cells in vitro." (PMID 34421345, 2021). "Emerging evidence also show an anti-inflammatory function of PF4 in melanoma and multiple myeloma through inhibition of STAT3 and upregulation of SOCS3 mediated mechanisms." (PMID 27223426, 2017). "Another comparison includes the COOH-Terminal Peptide of Platelet Factor-4 Variant (CXCL4L1/PF-4var47-70), which when injected intra-tumourally was also described as a successful therapy in B16F10 melanoma growth in vivo." (PMID 27973568, 2016). "First, the inhibitory effect of Sec23a on melanoma metastasis is mediated by secreted PF4." (PMID 34421345, 2021). "We next investigated whether the inhibitory effect of SEC23A on melanoma cell invasion is mediated by secreted PF4." (PMID 34421345, 2021). "However, when Pf4 status altered in melanoma cells, Sparc acted cooperatively to enhance the effect of Pf4." (PMID 34421345, 2021). "We then used the B16F10 melanoma model to verify our findings of PF4 expression in myeloid cells." (PMID 27223426, 2017). "Thus, Pf4 functions to inhibit the extend of melanoma metastasis." (PMID 34421345, 2021). "Here we show that PF4 and SPARC in the Sec23a-regulated secretome can act cooperatively to inhibit melanoma metastasis." (PMID 34421345, 2021). "To evaluate the role of Pf4 on melanoma metastatic progression in vivo, we inoculated OL-shPf4, POL-Sec23a-OE-shPf4 cells in which Pf4 was silenced and control cells to NOD/SCID mice by tail-vein injection." (PMID 34421345, 2021). "To understand the function of PF4 in metastasis, we utilized PF4 KO mice in C57Bl/6 genetic background and syngeneic B16F10 melanoma model." (PMID 27223426, 2017). "Using Pf4 Cx3cr1 mice to deplete CD206hi IMs expressing Cxcl13, Cxcl9, and Cxcl10, we demonstrate their essential role in TLS formation, lymphocyte recruitment, and tumor suppression in melanoma and lung adenocarcinoma." (PMID 40630529, 2025). "In our melanoma cell derived metastatic OL and POL cells that differ in metastatic colonization capability, Sparc appears to inhibit metastatic colonization in the presence of Pf4." (PMID 34421345, 2021). "Furthermore, SPARC can act cooperatively to enhance the inhibition of Pf4 on ERK phosphorylation and melanoma cell metastasis." (PMID 34421345, 2021).
melanoma (continued). "The most important finding of the current study is that PF4 transported by SEC23A, may cooperate with another secretory protein SPARC to inhibit melanoma metastasis via inhibition of MEPK/ERK activation." (PMID 34421345, 2021). "Another possibility is the over-expression of soluble molecules that inhibit or decrease metastasis in melanoma, including PF4/CXCL4, TR47, and MMP8, which could be used in combination with CAR T cells that target surface molecules." (PMID 34207884, 2021). "Specifically, platelet factor-4(PF4) transported by SEC23A, may cooperate with another secreted protein acidic and rich in cysteine (SPARC) to inhibit melanoma metastasis via inhibition of MEPK/ERK activation." (PMID 34421345, 2021).
antiphospholipid syndrome (10 papers, 2016 to 2026). A disorder caused by the presence of autoantibodies directed against phospholipids, causing a hypercoaguable state, which may result in blood clots, stroke, heart attack, and in women, significant pregnancy-related complications, including miscarriage and still birth. "In our patient, the antiphospholipid syndrome, in association with anti-PF4 and ITP post-vaccination, was an alternative diagnosis with overlapping clinical features with VITT." (PMID 36560433, 2022). "However, an alternative diagnosis of post-vaccine ITP, concurrent with a pro-coagulant state from antiphospholipid syndrome with concurrent anti-PF4 antibodies, was equally likely." (PMID 36560433, 2022). "In addition, PF4 is reportedly elevated in patients with antiphospholipid syndrome (APS) when platelet activity is increased, suggesting that PF4 could be a potential marker for DVT." (PMID 39189244, 2024). "The persistent strong positivity for anti-PF4 antibodies across three different ELISA kits, together with the transient and incomplete positivity of antiphospholipid antibodies, more likely related to the infectious syndrome than to true antiphospholipid syndrome, argues against this hypothesis." (PMID 41302191, 2025).
asthma (10 papers, 2016 to 2024). "PF4 encodes platelet factor 4, which is produced from activated platelets and is increased in the peripheral blood or BALF of patients with asthma." (PMID 36569909, 2022). "Several studies have provided evidence of platelet activation in asthma, as evidenced by an increase in platelet-derived mediators, such as platelet factor 4, beta-thromboglobulin (β-TG), RANTES, and thromboxane." (PMID 36292752, 2022). "The platelet activation markers such as β-thromboglobulin (β-TG) and platelet factor 4 (PF4), which are increased in the plasma of atopic dermatitis patients, were found to be higher when patients were afflicted with concomitant asthma and allergic rhinitis." (PMID 34440807, 2021). "Platelet activity in patients with pollen-induced seasonal allergic rhinitis and asthma, using plasma PF4 as an indicator, was found to increase during the grass pollen season and decrease in the off season." (PMID 34440807, 2021). "It has been reported that ELANE and PF4 are closely related to the pathogenesis of asthma." (PMID 36569909, 2022). "Also, Knauer14 has demonstrated significant changes in PF4 level of patients with pollen-induced asthma after bronchial provocation to ragweed extract." (PMID 27329923, 2017). "Moreover, asthma subjects had higher platelet factor 4 (PF4) (146.2 [144–148.3] vs. 97 [94.28–99.72] ng/ml, p < 0.0001), as well as raised α2-macroglobulin levels (15.07 [14.43–15.71] vs. 12.7 [12.1–13.3] nmol/l, p = 0.0002)." (PMID 28887505, 2017). "Outside the weed pollen season, the expression levels of LTF, PF4, and ELANE in the AR-asthma group were significantly higher than those in the AR group." (PMID 36569909, 2022). "PF4 and EPX are known to directly contribute to the induction of AHR in asthma models." (PMID 34256766, 2021). "It has been reported that platelet activation measured by plasma concentration of platelet factor 4 and beta-thromboglobulin is increased in AD patients, asthma, but not in allergic rhinitis and urticaria." (PMID 27127523, 2016). "The results of the qPCR showed that during the weed pollen season, the expression levels of ELANE and LTF in the AR-asthma group were significantly higher than those in the AR group, whereas the expression levels of PF4 in the two groups were not significantly different." (PMID 36569909, 2022). "In the present study, the AR-asthma group showed upregulated ELANE and PF4 expression compared to the AR group in the transcriptomic analysis, suggesting that increased elastase and platelet factor 4 may contribute to the development of allergic asthma from AR." (PMID 36569909, 2022). "PF-4 levels are shown to be considerably greater in individuals with severe asthma than in non-severe asthma, suggesting that the degree of platelet activation may rise as disease severity increases." (PMID 35682700, 2022). "Additionally, platelet factor 4 has been found to induce airway hyper-responsiveness in an asthma model.However, studies on the comparison of the expression levels of ELANE or PF4 between patients with AR and those with asthma are rare." (PMID 36569909, 2022). "We notice that in the qPCR tests, the measured expression level of PF4 in the AR group and AR-asthma group during the pollen season were not significantly different, and this might be related with the partial degradation to varying degrees in different RNA samples after several months of storage." (PMID 36569909, 2022).
colorectal cancer (10 papers, 2013 to 2024). A primary or metastatic malignant neoplasm that affects the colon or rectum. "OPN expression has been previously shown to enhance colon cancer cell growth, invasion and angiogenesis, and both IGFBP-2 and PF4 have been identified as biomarkers for the early detection of colorectal cancer." (PMID 30538296, 2019). "Protein levels of VEGF, PDGF and platelet factor 4 (PF4) in platelets are elevated in colorectal cancer patients compared to healthy control." (PMID 29677116, 2018). "Alternatively, platelets may express higher levels of PF4 in patients with cancer, which has been described for patients with colorectal cancer; where the level of PF4 in patients with cancer was double that of matched healthy control individuals." (PMID 31215484, 2019). "Interestingly, VEGF, platelet factor 4 (PF4), and PDGF are elevated in platelets of colorectal cancer patients." (PMID 28681240, 2017). "Study in patients with early colorectal cancer showed statistically significant increase in PF-4 in platelets coincident with a rise in pro-angiogenic factors, such as VEGF and PDGF, compared to healthy controls, while changes in plasma levels of PF-4 remained insignificant." (PMID 23800319, 2013).
prostate carcinoma (10 papers, 2010 to 2023). A carcinoma that arises from epithelial cells of the prostate gland. "Micronutrient supplementation has also been found to attenuate prostate cancer progression by inducing the expression of platelet factor-4, a megakaryocyte-specific inhibitor of angiogenesis." (PMID 37765058, 2023). "In patients with bone metastasis, including patients with breast and prostate cancer, elevated plasma PF-4 levels have been identified, being positively correlated with increased TGF-β levels." (PMID 25298751, 2014). "In prostate cancer cell lines, CXCL4/PF-4 and CXCL10/IP10, both ligands for CXCR3 receptor promote cell motility and invasiveness." (PMID 25298751, 2014). "It is conceivable, therefore, that the expression patterns of other proteins, in addition to PF-4, may be playing as intricate a role in controlling the progression of early-stage prostate cancer." (PMID 20525356, 2010). "In light of a recent report suggesting that upregulation of PF-4 may play a crucial role in the early stages of several cancers, we propose here that upregulation of this peptide in our study was crucial in preventing angiogenesis at the tumor site in early prostate cancer." (PMID 20525356, 2010). "Since CXCL4/PF4 and CXCL10/IP10 represent the main CXCR3 ligands found during platelet degranulation and thus any hemorrhage and deep in reactive/wounded stromal compartment respectively, we examined functions of these two CXCR3 chemokines on prostate carcinoma cell functioning." (PMID 22236567, 2012).